ABLIM1 (actin binding LIM protein 1)
Diseases named in the same sentence as ABLIM1 in open-access papers (continued):
Sharing a sentence is not in itself a finding about the gene and the disease.
tumor (10 papers, 2008 to 2025). "According to our data, decreased ABLIM1 was associated with larger tumor size, whereas ABLIM1 overexpression resulted in impaired GBM growth." (PMID 36583064, 2022). "Although the precise molecular mechanisms remain to be elucidated, current evidence supports the clinical value of ABLIM1 as a putative tumor suppressor." (PMID 40831931, 2025). "The biological function of ABLIM1 was studied using various in vitro cell experiments and in vivo tumor xenografts and metastasis models." (PMID 38228802, 2024). "Further tumor xenografts and liver metastatic models validated the oncogenic role of ABLIM1 in vivo." (PMID 38228802, 2024). "In the tumor xenograft experiment, ABLIM1 knockdown in HCT 116 cells remarkably slowed down the subcutaneous tumor growth." (PMID 38228802, 2024). "Consistently, the p65, CCL20, and Ki-67 expressions in tumor xenografts were repressed after ABLIM1 knock-down, supporting ABLIM1 modulates the IĸBα/NF-κB/CCL20 axis to promote CRC progression." (PMID 38228802, 2024). "A subcutaneous xenograft model was generated using nude mice to validate the tumor-related effect of ABLIM1 in vivo." (PMID 36583064, 2022). "Nevertheless, we provided initial evidence regarding the tumor-related role of ABLIM1 in GBM from clinical, cellular, and in vivo aspects." (PMID 36583064, 2022). "We applied patients' age, tumor size, and ABLIM1 level into a Cox hazard regression model to identify independent prognostic factors." (PMID 36583064, 2022). "In contrast, in CRC, the availability of such cofactors may redirect ABLIM1 activity toward NF-κB activation and tumor progression." (PMID 41409245, 2025). "Taken together, these findings suggest ABLIM1 may closely associate with CRC relapse and play a role in tumor malignant progression." (PMID 38228802, 2024). "Knock-down of ABLIM1 in CRC cell lines by lenti-virus leads to inhibited cell proliferation, migration, and invasion capabilities in vitro and impaired growth of tumor xenografts and liver metastasis lesions in vivo, while ABLIM1 overexpression accelerates tumor growth and invasion in vitro." (PMID 38228802, 2024). "Consistently, ABLIM1 exerted tumor-suppressing functions in mice models." (PMID 36583064, 2022). "ABLIM1 level was negatively correlated with tumor size (P = 0.029), indicating that ABLIM1 may exert tumor-suppressive effects in GBM." (PMID 36583064, 2022). "Overall, ABLIM1 may serve as a tumor-promoting gene and has a potential prognostic prediction value in HCC." (PMID 33061800, 2020). "Importantly, the IĸBα/NF-κB blockade by BAY11-7082 further abolished the effect of ABLIM1 overexpression on cell proliferation, migration, and invasion, implying IĸBα phosphorylation mediated NF-κB p65 activation is involved in the tumor-promoting role of ABLIM1." (PMID 38228802, 2024). "Our analyses unveiled four hub genes—ABLIM1, FHL5, MAP3K8, and TOP2A—that consistently emerged as differentially expressed across all tumor samples when compared to normal tissue." (PMID 40831931, 2025). "In line with mRNA-level changes, protein levels of ABLIM1, FHL5, and MAP3K8 decreased progressively from normal tissue to tumor tissues, whereas TOP2A showed an opposite trend." (PMID 40831931, 2025). "ABLIM1, FHL5, and MAP3K8, on the other hand, were downregulated in ULMS, indicating their potential tumor-suppressive roles." (PMID 40831931, 2025). "Four hub genes—ABLIM1, FHL5, MAP3K8, and TOP2A—were consistently dysregulated in both tumor types relative to normal tissue, suggesting their common role in tumor development." (PMID 40831931, 2025). "Other studies showed upregulation of ABLIM1 in CRC patients and demonstrated its function in promoting tumor growth and metastasis in vitro." (PMID 39766812, 2024). "Since the Wnt-GSK-3β signaling pathway is well known for its tumor-related function, GSK-3 and ABLIM1 probably interact with malignancies." (PMID 36583064, 2022).
tumor (continued). "Since ABLIM1 is upregulated in CRC, inhibiting its expression through siRNAs might robustly reduce tumor growth and metastatic burden in CRC patients." (PMID 41409245, 2025). "Thus, it is reasonable to suspect ABLIM1 as an oncogene in CRC, which could promote tumor cell proliferation, migration, and invasion." (PMID 38228802, 2024).
ABLIM1 also shares sentences with these, for which no sentence is quoted: melanoma (3 papers); Alzheimer disease (1); Autoimmunity (1); esophageal cancer (1); intrahepatic cholangiocarcinoma (1); oligodendroglioma (1); pancreatic adenocarcinoma (1); pancreatic ductal adenocarcinoma (1); pulmonary disease (1).